IGF1 (insulin like growth factor 1)
Diseases named in the same sentence as IGF1 in open-access papers (continued):
Sharing a sentence is not in itself a finding about the gene and the disease.
diabetes (continued). "In patients with diabetes mellitus, a frequent comorbidity in acromegaly, IGF-1 would be affected due to the higher proteolysis of IGF-1 binding protein 3 (IGFBP-3), one of the main binding proteins." (PMID 34557164, 2021). "Decreased levels of insulin-like growth factor-1 (IGF-1) were reported in age-related conditions such as sarcopenia, diabetes, cardiovascular diseases, frailty, and the like (117, 121 of 4)." (PMID 34306314, 2021). "Insulin-like growth factor 1 (IGF-I) and blood lipids were normal, while fasting glucose and HbA1c were slightly elevated in three men with diabetes." (PMID 34204309, 2021). "Conversely, the mirrored effect for high IGF‐1 was most prominent in IGF‐1 quintile 5 for diabetes and vascular disease: Within IGF‐1 quintile 5, younger individuals had the lowest hazard for incident disease, with risk increasing for older age groups." (PMID 34363732, 2021). "Patients with diabetes mellitus have a lower incidence of prostate cancer due to low androgen, insulin, and IGF-1 levels." (PMID 33921222, 2021). "Diabetes also promotes the production of IGF-1 in the liver and inhibits the secretion of sex hormone-binding globulin (SHBG) and IGF-binding protein (IGFBP)." (PMID 33842335, 2021). "It is also reported that reduced IGF-1 is a cause of diabetes mellitus (DM) via the GH/IGF-1 axis." (PMID 33746806, 2021). "Insulin and IGF-1 are neurotrophic for retinal neurons via activation of the Akt pathway, a pathway specifically impaired by diabetes in the retina and metabolic stress conditions in cultured neurons." (PMID 33915127, 2021). "Previous studies have been reported that people with a low IGF-1 level are prone to have diabetes mellitus." (PMID 34880907, 2021). "This discovery further confirms that insulin and IGF-1 are important factors for adipocyte metabolism in many disease models, including diabetes." (PMID 34563222, 2021). "IGF-1 levels have been reported to be down-regulated in type 1 diabetes mellitus (T1DM), yet up-regulated in type 2 diabetes mellitus (T2DM)." (PMID 33557137, 2021). "Several studies have indicated that vascular actions of insulin and IGF-1 are impaired in some cardiovascular disorders, such as hypertension and diabetes." (PMID 34203897, 2021). "Biological mechanisms linking diabetes to cancer include both hyperglycemia and hyperinsulinemia, increased bioactivity of IGF-1, oxidative stress, dysregulations of sex hormones, and chronic inflammation." (PMID 34208601, 2021). "By contrast, immunoblotting showed marked reduction of the mature IGF-1 peptide in response to diabetes." (PMID 33915127, 2021). "Collectively, these results show that the effects of diabetes and high glucose on IGF1/IGF1R expression are tissue-specific." (PMID 33575847, 2021). "The known pathogenesis of diabetes mellitus (DM) in acromegaly is mainly based on growth hormone (GH) and insulin-like growth factor-1 (IGF-1) excess." (PMID 34217172, 2021). "This study assesses the serum levels of insulin-like growth factor-1 (IGF-1) and sclerostin as markers of decreased bone formation in premenopausal women with type 2 diabetes mellitus." (PMID 34690653, 2021). "Differentially methylated genes of m6A are enriched in insulin regulatory and diabetes-related metabolic pathways and several genes in the insulin/IGF1-AKT-PDX1 signal transduction pathway displayed reduced methylation levels." (PMID 34950107, 2021). "High levels of leptin in the HFD mice and increased plasma glucose, insulin and IGF-1 in the serum indicated leptin resistance and insulin resistance, suggesting the onset of diabetes." (PMID 32639947, 2020). "This, together with the reduced levels of miR-322-5p that was previously found important for targeting IGF-1 signaling, suggests a potential involvement of SC expression of sortilin in diabetes or diabetic complications." (PMID 33114403, 2020).
diabetes (continued). "In a longitudinal cohort of independently living older adults in generally good health, we found that IGF-1 and associated proteins predicted all-cause mortality and incidence of age-related diseases, including MDCI, diabetes, and composite incident morbidity." (PMID 32492897, 2020). "The blood glucose levels of over 13.9 mmol/L are regarded as diabetic, and the results showed that the mice in db/db group and IGF-1-treated group had diabetes." (PMID 32024487, 2020). "High circulating levels of GH/IGF1 and concurrent presence of comorbidities like diabetes and hypogonadism in patients with acromegaly possibly abrogates the beneficial effect of GH/IGF1 on periodontal health." (PMID 33154456, 2020). "Studies examining the epigenetic status of the IGF1 gene in deregulated lipid metabolism, cardiovascular disease, and diabetes are limited." (PMID 32678007, 2020). "During diabetes monitoring and follow-up to improve glycemic control, the serum level of IGF-1 usually increases." (PMID 33905470, 2020). "For example: IGF1, IGF2 and LEPR, which have previously been associated with diabetes, while STAT5B and ROCK1 have shown weaker associations to the disease." (PMID 32735660, 2020). "There is controversy about the serum IGF-1 level that correlates with the progression of retinal neovascularization in clinical diabetes and increased or decreased concentrations of IGF-1 in the vitreous or serum levels of patients with DR." (PMID 33905470, 2020). "Insulin like growth factor-1 (IGF-1) is a key player in human growth and development and its perturbation can cause severe diseases including cancer, acromegaly, diabetes, thyroid eye disease, acne and psoriasis." (PMID 33276615, 2020). "Cancers share similar phenotypes with diabetes such as higher insulin and Insulin-like growth factor 1 (IGF-1) or leptin/adiponectin secretion and immune abnormalities." (PMID 32498358, 2020). "IGFPB-1 is regarded as the primary regulator of IGF-1 bioactivity and has an important part in the progression of diabetes and diabetes-related complications." (PMID 33905470, 2020). "A high protein consumption elevates insulin-like growth factor 1 (IGF-1), proved to be linked to a high diabetes risk." (PMID 30931309, 2019). "Most studies on the relationship between IGF-1 and renal disease are related to diabetes mellitus or hyperglycemia." (PMID 31540583, 2019). "GH and IGF-1 levels decline rapidly and sharply after successful surgery, which normalizes the glucose metabolism in 23–58% of patients with preoperative diabetes per previous studies." (PMID 31736874, 2019). "The administration of somatostatin analogs to patients with type 1 diabetes mellitus has also been reported to reduce serum IGF-1 and urinary albumin." (PMID 31540583, 2019). "Recombinant human IGF-1 (rhIGF-1) has been evaluated as treatment for diabetes, with evidence of improved glycemic control but significant adverse effects including worsening diabetic retinopathy." (PMID 31416218, 2019). "Insulin-like growth factor 1 (IGF-1) was the main factor measured in both studies using diabetes-induced model." (PMID 30581489, 2018). "Despite this, our data suggests that the GH and IGF-1 excess of acromegaly has significant effects on the myocardium over and above any changes induced by diabetes alone." (PMID 29596445, 2018). "Induction of diabetes using streptozotocin in miR-483 transgenic mouse model increased cardiomyocyte apoptosis by silencing insulin growth factor 1 (IGF-1)." (PMID 30013975, 2018). "In several pathologies such as type 1 diabetes mellitus (T1DM) antiinflammatory properties have been attributed to the IGF-1/IGF-IR system in the CNS by counteracting the inflammatory milieu triggered by microglial activation in the hypothalamus." (PMID 30026694, 2018). "Collectively, we suggest that diabetes combined with hypothyroidism affects testicular development by regulating IGF-1/testosterone signaling." (PMID 29940839, 2018).
diabetes (continued). "Preclinical rat studies have shown neonatal hypoxia-ischaemia as a precursor to diabetes, metabolic syndrome and stroke, and IGF1 treatment offers neuroprotection after hypoxia-ischaemia." (PMID 30165597, 2018). "Over the long-term, metabolic complications related to diabetes result in significant alterations in growth hormone (GH) and insulin-like growth factor-1 (IGF-1)." (PMID 29351335, 2018). "Insulin‐like growth factor‐1 (IGF‐1) is a fetal anabolic growth factor which also impacts β‐cell mass in models of β‐cell injury and diabetes." (PMID 30175552, 2018). "The relationship of IGF-1 to fetal growth across the different types of diabetes requires clarification." (PMID 30108547, 2018). "For example, chronic oxidative damage in the kidneys of individuals with diabetes is mediated by increased insulin-like growth factor 1(IGF-1) and nicotinamide adenine dinucleotide phosphate(NADPH) oxidase enzymes." (PMID 29554942, 2018). "miR-1 was also found to play an important role in diabetes by directly targeting insulin-like growth factor-1 and its receptor or signaling cascades related to IGF pathway." (PMID 30013975, 2018). "Low IGF-1 in type 1 diabetes as found in this study at diabetes diagnosis in adolescents has been ascribed to insulin deficiency as well as poor glycemic control." (PMID 29744370, 2018). "Blood IGF-1 level in patients with diabetes and depression has significant changes, which is consistent with the result of another study." (PMID 30181997, 2018). "Diabetic gastroparesis is a common complication of diabetes mellitus (DM) that is characterized by decreased serum insulin and insulin-like growth factor-1 (IGF-1)." (PMID 28931726, 2017). "In animals submitted to 37 days of diabetes, IGF-1 mRNA expression in the hypertrophied EDL muscle was markedly elevated (about 10-fold in the control and 5-fold in the diabetic groups)." (PMID 29123487, 2017). "Taken together, these results support a pathway in which reduced IGF-1 in diabetes leads to suppressed activation of the mTOR pathway, which further reduces IGF-1." (PMID 28729536, 2017). "Mouse studies have revealed that high protein intake increases insulin-like growth factor 1 (IGF-1) levels, which are in turn associated with an increased risk of cancer, diabetes, and overall mortality." (PMID 28388917, 2017). "Our data suggest that in the setting of diabetes, reduced IGF-1, impaired mTOR pathway activation and reduced IL-15 in the epidermis function coordinately to promote altered DETC homeostasis and delayed skin wound closure." (PMID 28729536, 2017). "The effect of diabetes on the cancer progress can be also interpreted using insulin and insulin-like growth factor 1(IGF-1) signaling pathways." (PMID 28977962, 2017). "Seven patients had diabetes mellitus, but were compensated at the time of IGF-1 measurement and OGTT." (PMID 28977166, 2017). "Consistent data from multiple studies (in vitro and in vivo) demonstrate the association between IGF-1 deficit and deregulated lipid metabolism, cardiovascular disease (CVD), diabetes, and altered metabolic profile of diabetic patients." (PMID 26733412, 2016). "IGF-1 levels also decrease with age and in diabetes, both coinciding with declined cognitive abilities." (PMID 27227831, 2016). "It is confirmed that increases in IGFBP-3 expression due to diabetes would attenuate the cellular response to IGF-1 through the high affinity binding of IGF-1 to IGFBP-3." (PMID 26823979, 2016). "The search plan was made in Medline for Pubmed with the following mesh terms: IGF-1 and “metabolism, carbohydrate, lipids, proteins, amino acids, metabolic syndrome, cardiovascular disease, diabetes” between the years 1963–2015." (PMID 26733412, 2016). "Decreased IGF-1 levels with aging and diabetes reduce penile NOS expression and reduced availability of NO are among the causal factors implicated in ED." (PMID 26823979, 2016).
diabetes (continued). "Secondly, upregulated insulin-like growth factor 1 (IGF-1) in diabetes patients increases tumor cell proliferation and inhibits apoptosis, and associated with an increased risk of bladder cancer." (PMID 27286260, 2016). "IGF-1 and insulin share major downstream regulation pathway and both are engaged in cancerogenesis and diabetes." (PMID 27405474, 2016). "Nevertheless, it is noteworthy that the inverse correlation between IGF-1 and diabetes only prevails in younger individuals (<65 years), establishing that this deficiency can lead to MetS—as aging can be considered an IGF-1 deficiency condition." (PMID 26733412, 2016). "Catalpol treatment could improve diabetes-associated impaired renal functions and ameliorate pathological changes in diabetic kidneys, while such beneficial effects correlate with a down-regulation of Grb10 expression and a concomitant up-regulation of IGF-1/IGF-1R signaling in diabetic kidneys." (PMID 26986757, 2016). "The link between IGF1-related formation of AGEs and resistance of bone to fracture may have important implications for understanding the role of protein matrix in bone toughness as well as in the development of new diagnostic tools and treatments for osteoporosis or diabetes." (PMID 25629402, 2015). "We found that Acu-LFES improves muscle regeneration by reversing the diabetes-induced suppression of IGF-1, p-Akt (protein anabolic markers), and p-mTOR (protein synthesis markers)." (PMID 26230945, 2015). "Previous studies have reported reduced levels of circulating IGF1 as a common feature in diabetes, with the highest reductions seen at older ages and with longer duration of disease." (PMID 26025657, 2015). "As in mice, mutations causing growth hormone (GH) resistance resulting in low circulating levels of IGF-1 have been reported to confer protection against the development of cancer and diabetes in men." (PMID 26568155, 2015). "Our results and those of other investigators have shown that IGF-1 plays a central role in controlling the muscle wasting of diabetes and other catabolic disease." (PMID 26230945, 2015). "Initial IGF-1 was significantly higher for the group of patients diagnosed with diabetes, as previously shown by our group especially if they were over the age of 50." (PMID 25996963, 2015). "In this study, we identified a simple non-pharmacologic treatment, Acu-LFES, which is able to increase IGF-1 signaling and prevent diabetes-induced muscle atrophy by stimulating muscle regeneration." (PMID 26230945, 2015). "The contribution of IGF-1 vs. diabetes alone or in combination in the development of extra-pituitary neoplasms warrants further investigation." (PMID 25996963, 2015). "Other researchers and we have found that decrease of IGF-1 is a common pathway for muscle wasting, and upregulation of the IGF-1 signaling pathway counteracts muscle atrophy in diabetes and chronic renal failure in animal models." (PMID 26230945, 2015). "In the study, the recombinant human IGF1 delivered by minipumps to maintain a serum level of ∼350 pg/ml is efficacious in the treatment of diabetes." (PMID 26398949, 2015). "This cross-sectional study was designed to give insights into relationship between Insulin-Growth-Factor 1 (IGF-1) levels and diabetic retinopathy (DR) in a sample of thalassemia major (TM) patients with insulin dependent diabetes mellitus (IDDM)." (PMID 26075045, 2015). "In patients with diabetes, partial control of glucose metabolism is due to inadequate suppression of GH and IGF1 after one year of treatment." (PMID 26361517, 2015). "Mice in which the genes for growth hormone (GH) or GH receptor (GHR−/−) are disrupted from conception are dwarfs, possess low levels of IGF‐1 and insulin, have low rates of cancer and diabetes, and are extremely long‐lived." (PMID 26268661, 2015). "We conclude that Acu-LFES is effective in counteracting diabetes-induced skeletal muscle atrophy by increasing IGF-1 and its stimulation of muscle regeneration." (PMID 26230945, 2015).
diabetes (continued). "Insulin, insulin-like growth factor-1 (IGF-1), and certain hormones play an important role in promoting neoplasia in diabetics." (PMID 25426078, 2014). "The duration of acromegaly waslongest in the diabetes group, and IGF1 levels were higher in subjects with ECMDs anddiabetes than in individuals with NGT." (PMID 24692509, 2014). "CRC initiation and promotion by diabetes is due to diabetes-induced increase in growth factors (e.g., insulin, IGF-1) and inflammatory adipo/cytokines (e.g., TNFα, IL-6)." (PMID 25375205, 2014). "In this study, we conducted combined intervention of IL-10 and IGF-1 in NOD mice with diabetes at onset stage and evaluated its protective effects on the residual islet β- cells, hoping to provide a theoretical basis for early clinical treatment of T1D." (PMID 24663217, 2014). "Diminished production of pro-angiogenic growth factors, such as IGF-1 and VEGF, is thought to contribute to the impaired angiogenesis observed in chronic wounds associated with diabetes." (PMID 24618702, 2014). "This is especially cogent given that up-regulation of IGF-1 within the eye leads to appearance of diabetes-like alterations, which cautions against direct use of this growth factor in promoting axonal repair." (PMID 23349896, 2013). "The aim of the present study was to investigate the association between intra-prostatic levels of IGF-1, IGF-2 and BPH, as well as to evaluate the role of locally expressed IGFBP-3 in BPH development in different states of pre-diabetes." (PMID 24367483, 2013). "In the ERMs, the mRNA level of IGF1 was significantly higher in the patients with diabetes (median = 271 mRNA copies/μg of total RNA) compared to the control iERMs of nondiabetic group (median = 85 mRNA copies/μg of total RNA)." (PMID 24379526, 2013). "Curcumin was antidiabetic therapy, induced hypoglycemia by up-regulation of IGF-1 gene and ameliorate the diabetes induced oxidative stress via increasing the availability of GSH, increasing the activities and gene expression of antioxidant enzymes and Bcl2." (PMID 24364912, 2013). "Human studies have shown a positive correlation between IGF-1 and mental abilities, and IGF-1 has been employed for the treatment of diabetes, growth failure, and motor neuronal disorders." (PMID 22720172, 2012). "It has also been reported to improve the overall metabolic condition in diabetes as a result of induction of insulin-like growth factor-1 and reduced oxidative stress, which is a problem in type 2 diabetes." (PMID 23304216, 2012). "Individuals with Laron syndrome who carry mutations in the growth hormone receptor (GHR) gene that lead to severe congenital IGF-1 deficiency with decreased insulin/IGF-1 signaling (IIS) exhibit reduced prevalence rates of acne, diabetes and cancer." (PMID 21699736, 2011). "Transcription of insulin-related genes (Ins, Igf1, and Igf2) has been analyzed in the thymus of diabetes-resistant (BBDR) and diabetes-prone (BBDP) rats, another model of T1D." (PMID 21647405, 2011). "Poor diabetes control predicted lower IGF-1 (r2 = 0.21) and greater IGFBP-1 (r2 = 0.39), IGFBP-5 (r2 = 0.38), and bone-specific alkaline phosphatase (BALP; r2 = 0.41, p < 0.05)." (PMID 18665784, 2008). "Medical literature suggests that well controlled biochemical and genetic studies are required to establish the link between insulin, IGF-1, diabetes and cancer." (PMID 17953765, 2007). "The aim of this pilot study was to investigate the effect of two regimes of amino acids infusion, before and during hysterectomy, on the surgery induced decrease in IGF-1 and "diabetes of injury"." (PMID 17212815, 2007). "Amino acid infusion during surgery attenuates the decrease in IGF-1 and diminishes the "diabetes of injury"." (PMID 17212815, 2007). "Chronic inflammation offers another explanation for low IGF-1 in uncontrolled diabetes." (PMID 41393761, 2025).